TNF (tumor necrosis factor)
Diseases named in the same sentence as TNF in open-access papers (continued):
Sharing a sentence is not in itself a finding about the gene and the disease.
Obesity (continued). "Furthermore, since obesity is associated with the inflammation of adipocytes, as well as the development of insulin resistance and type II diabetes mellitus, we determined the anti-inflammatory properties of TPDM6315 extracts against TNF-α induced adipocytes." (PMID 37367060, 2023). "By the assumption that obesity is an important constitutional factor for induction, progression, or recurrence of AF, the current results showed significantly higher serum levels of studied adipocytokines; visfatin and adiponectin, and TNF-α in patients of RAF than in NO RAF groups." (PMID 37466800, 2023). "Furthermore, obesity leads to low-grade chronic inflammation and in obese individuals, in addition to the synthesis of pro-inflammatory cytokines (such as IL-6 and TNFα), a reduction of anti-inflammatory cytokines (such as adiponectin) is observed in adipose tissue." (PMID 37653524, 2023). "In addition, the gut microbiota can contribute to a low-grade systemic inflammatory state of fat deposition through several molecular interactions regulating innate immunity and inflammatory signaling (most notably TNF-α), indirectly participating in the onset of obesity." (PMID 36786619, 2023). "Furthermore, the increase in both blood TNF‐α and IL‐6 due to obesity was suppressed in KO mice." (PMID 37845194, 2023). "Furthermore, TNF-α derived from adipocytes was also shown to induce PD-L1 expression in HCC tumor cells of obese mice, which may mechanistically link obesity with the progression of NAFLD-associated HCC." (PMID 37958479, 2023). "By inhibiting TNF-α-induced adhesion molecules, it exerts anti-inflammatory effects, and via binding to the transcription factor peroxisome proliferator-activated receptor-α, it activates downstream pathways which improve, among others, insulin resistance, hypertension, and obesity." (PMID 37371951, 2023). "However, obesity-related changes in adipocyte secretory profile (including, e.g., excess synthesis of interleukin 6 (IL-6) and tumor necrosis factor-alpha (TNFα)) attract pro-inflammatory M1 macrophages to perpetuate pro-inflammatory cytokine signaling to trigger adipocyte cell death." (PMID 36979669, 2023). "For example, the important relationship between specific steps in the development of colon cancer and obesity-induced inflammation has been pointed out to be mediated by inflammatory cytokines secreted by macrophages, such as interleukin 6 (IL-6) and tumor necrosis factor-alpha (TNF-α)." (PMID 36982615, 2023). "Besides the elevated free fatty acid levels, other substances secreted by the adipocytes that are augmented (tumor necrosis factor—TNF-α, resistin) or decreased (adiponectin) in obesity inhibit insulin secretion and insulin-mediated glucose uptake, and lead to insulin resistance." (PMID 37367903, 2023). "Moreover, obesity may increase osteoclastogenesis and bone resorption through upregulating proinflammatory cytokines, such as IL-6 and TNF-α, which are capable of stimulating osteoclast activity through the RANKL/RANK/OPG pathway." (PMID 37685327, 2023). "Furthermore, in the adipose tissue of several obesity models, TNF-α expression levels are high." (PMID 36986440, 2023). "However, it remains elusive whether the metabolic (such as exposure to LPS, PA, or OA) and ER stresses, as found under conditions of obesity or metabolic syndrome, can cooperate to amplify the expression of TNF-α in monocytic cells." (PMID 37894865, 2023). "However, the limited therapeutic efficacy of using anti-TNF-α therapies for improving obesity-induced insulin resistance and glucose metabolism suggests that macrophages in adipose tissue may also influence metabolic status through other pathways." (PMID 38169960, 2023). "However, in one study, obesity class II women had higher TNF-α levels compared to lower BMI groups." (PMID 36520252, 2023).
Obesity (continued). "In short, whether it is potentiated by obesity and/or T2DM, inflammation is caused by changes in innate and adaptive immunity, high levels of circulating pro-inflammatory cytokines, including TNF-α, MCP-1, and IL-6, elevation of prothrombotic factors, high viral entry, and decreased viral clearance." (PMID 37888519, 2023). "Published human studies investigating the association of TNF-α antibodies with obesity and IR have so far failed to provide efficacy in favour of a significantly improved metabolic state that would justify their use in clinical practice as a therapeutic option." (PMID 37239098, 2023). "In obesity, an altered balance towards increased pro-inflammatory adipokines like TNF-α, IL-6 and IL-8 is present and may mediate the obesity-related state of inflammation of obese patients and favor the onset of metabolic disturbances and their increased cardiovascular risk." (PMID 37571368, 2023). "Last but not least, as both obesity and NAFLD may lead to the development of HCC, and in the absence of any approved medication specifically for NAFLD, it should be evaluated whether targeting obesity may prevent NAFLD-associated HCC, by affecting adiponectin and/or TNF-α production." (PMID 37958479, 2023). "Obesity in pregnancy produces the abnormal production of hormones such as adipokines, TNF, and IFNs, as well as the circulating short-chain saturated fatty acids, that activate the immune system, which may compromise the effector function of antiviral mechanisms." (PMID 36851534, 2023). "Interestingly, patients with a high visceral to total fat ratio also had higher levels of IL-6 and tumor necrosis factor α, suggesting that the detrimental effects of obesity may be mediated by inflammation." (PMID 37225730, 2023). "Moreover, it has been described that TNFα and IL-6, which are secreted by adipocytes, upregulate PD-L1 in hepatoma and B16-F1 cells, which may be at least partially involved in the role of obesity in promoting tumor progression." (PMID 37107188, 2023). "Gouranton and his co-workers demonstrated in their study that lycopene had a moderating effect on the formation of IL-1β, IL-6 and TNF-α in adipose tissue and eventually might prevent or reduce the incidence of obesity-related diseases including insulin resistance." (PMID 36826001, 2023). "Moreover, HIIT-induced IL-10 overexpression may suppress IL-β, IL-6, and TNF-α in mononuclear cells challenged with lipopolysaccharide and the transcription of IL-8 in polymorphonuclear leukocytes in individuals with obesity." (PMID 37608837, 2023). "Moreover, the Twist1 expression in human WAT was relatively low under the circumstances of obesity and insulin-resistance, which may be mediated by an increased sensitivity to the proinflammatory effect of TNF-α." (PMID 37784111, 2023). "Therefore, it seems necessary to compare the results obtained with other potential indicators in the future, like molecular indicators including variants of different risk alleles to determine polygenic or common obesity, including FTO, TNF-α, MC4R, ENPP1 genes, etc.." (PMID 37761477, 2023). "Obesity is a proinflammatory state, and the adipose tissue propagates inflammation by recruitment of macrophages via chemokines such as monocyte chemoattractant protein-1, and via elaboration of cytokines and chemokines such as leptin, interleukin-6, and tumor necrosis factor α." (PMID 37535415, 2023). "The tissue inflammatory state during obesity may be caused by TLR-4/NF-κB pathway activation in macrophages via FFA action, which promotes the synthesis and secretion of proinflammatory cytokines, including IL-6, TNF-α, IL-1β, and IL-18." (PMID 37372966, 2023). "Furthermore, the chronic inflammation observed in obesity may be sustained through the persistent activation of p38MAPK and NF-κB signaling and the secretion of the pro-inflammatory cytokines IL-6 and TNFα." (PMID 37821967, 2023).
Obesity (continued). "The analysis of other inflammatory markers may provide more information about the chronic and low-grade systemic inflammation characteristic of obesity since other authors have already found a relationship between tumor necrosis factor-α (TNF-α), adipokines, and interleukin-6 and BMI20." (PMID 37474543, 2023). "In the context of RA, obesity may contribute to its pathogenesis by fostering a chronic pro-inflammatory state, characterized by elevated levels of tumor necrosis factor-α (TNF-α) and interleukin-6 (IL-6), which in turn stimulate autoantibody production and inflammatory cell activation." (PMID 37474953, 2023). "Obesity was associated with decreased serum levels of Eotaxin and KC, and elevated serum levels of G-CSF, TNF-α in offspring mice, while KD alone was associated with elevated serum levels of G-CSF, IL-1b, IL-6, RANTES, TNF-α and decreased serum levels of IL-1a, IL-9, IL-12 (p70)." (PMID 37686855, 2023). "For example, increased infiltration of classically activated macrophages (M1) into the adipose tissue and increased production of TNFα and IL-6 are hypothesized to interfere with the normal activity of insulin receptors and contribute to the development of insulin resistance in obesity." (PMID 35684160, 2022). "The lack of differences in TNF-α levels between groups may be accounted for by the fact that an increase in TNF-α is associated not only with obesity, but also with cachexia." (PMID 36428528, 2022). "Moreover, infusion of OCN could substantially downregulate inflammatory related genes (e.g., tumor necrosis factor α (TNFα), IL-1β, and IL-6) and transcription factors in a monosodium glutamate-induced mouse model of obesity." (PMID 35625743, 2022). "In addition, it has been reported that overproduction of TNF-α and the other endogenous proinflammatory cytokines play a substantial role in the pathophysiology of endothelial dysfunction observed in obesity, suggesting that obesity is a low-grade inflammatory disease." (PMID 35206342, 2022). "During obesity, the protective interleukins (IL-17-producing Th17 cells, IL-10-secreting regulatory T (Treg) cells, and IL-22) are reduced, while there is a more significant release of pro-inflammatory cytokines such as tumor necrosis factor (TNF-α) and interferon (IFNγ)." (PMID 35966101, 2022). "The expansion of adipose tissue stores in obesity, particularly visceral adipose tissue, leads to an imbalance of these opposing groups of peptides, such that the level of pro‐inflammatory and pro‐diabetic adipokines, such as TNF‐α and monocyte chemoattractant protein‐1 supersedes." (PMID 36245259, 2022). "Furthermore, obesity-related increases in TNF- can directly inhibit LH secretion." (PMID 35897011, 2022). "Interplay between hormones and cytokines may also be important as TNFα, which reduces insulin sensitivity and has been shown to be overexpressed in people with obesity, is partially mediated by leptin in addition to IL-2, and IL-6 cytokines that increase T-cell expansion and liver disorders." (PMID 36143948, 2022). "It is well known that obesity leads to an elevated inflammatory response and that excess adipose tissue increases the secretion of pro-inflammatory cytokines, markers of inflammation, including interleukin 6, interleukin 8, tumor necrosis factor, and C-reactive protein." (PMID 36388204, 2022). "Moreover, the levels of IL-10 (P < 0.001), IL-4 (P < 0.001), and TNF-α (P < 0.001) in the sarcopenia group were higher than those in the non-sarcopenia group after adjusting for sex, age, hypertension, blood lipid concentration, and obesity." (PMID 36160136, 2022). "However, 50 patients with obesity-related metabolic diseases were treated with TNF-α inhibitor etanercept for 6 months, which could significantly improve fasting blood glucose and increase adiponectin content in blood." (PMID 35757707, 2022).
Obesity (continued). "Inflammation caused by obesity and lack of physical activity has been considered a primary cause of type II diabetes and atherosclerosis, and is associated with increases in pro-inflammatory cytokines IL-6 and TNF-α." (PMID 36292427, 2022). "Increasing systemic TNF-α and IL-6 in obesity might impair insulin signaling pathway." (PMID 35409099, 2022). "Additionally, this cytokine may influence the genesis of obesity because it was suggested in animal experiments that the deletion of receptor 1 of TNF-α protects from diet-induced obesity through increased thermogenesis." (PMID 35631100, 2022). "Pro-inflammatory cytokines, such as TNF-α and IL-6, could contribute to systemic insulin resistance or metabolic disorder in obesity, while anti-inflammatory cytokines, such as IL-10 and IL-4, could prevent diet-induced obesity and insulin resistance." (PMID 35807812, 2022). "In obesity, the accumulation of fat and enlargement of adipocytes contribute to the dysfunctionality of these cells as well as that of endothelial cells and macrophages (M1-polarized macrophages), increasing the secretion of a range of adipokines including TNF-α." (PMID 36010524, 2022). "Similarly, it has been described how liraglutide can improve the Dermatology Life Quality Index (DLQI) of diabetic patients with psoriasis and decrease the expression of IL-17, IL-23, and TNF-α, all pro-inflammatory cytokines involved in psoriasis and obesity pathogenesis." (PMID 35886846, 2022). "Furthermore, both TNF-α and CL-316243 in vitro and obesity in vivo induced Cebpb in our RNA-Seq data sets, suggesting that CEBPB may be driving Trib1 induction." (PMID 34847077, 2022). "For example, in Polish women, the levels of TNF-α varied significantly (p < 0.001) from 2.9 ± 2.2 pg/mL in the lean participants to 6.5 ± 3.1 pg/mL in overweight individuals, 6.8 ± 3.1 pg/mL in participants with obesity, and 7.4 ± 2.6 pg/mL in very obese participants." (PMID 36010524, 2022). "In our previous study, we observed that intervention with MSS reduced obesity caused by a high-fat diet, lowered elevated blood triglycerides, cholesterol and LDL cholesterol, and had an ameliorating effect on inflammatory factors such as TNF-α and IL-6 in vivo, as well as on their intestinal flora." (PMID 36407552, 2022). "Moreover, adipose tissue is a reservoir of proinflammatory cytokines, mainly IL-6 and TNFα, and obesity may promote expansion of Th17 cells." (PMID 36159785, 2022). "In addition, obesity can be considered a low-grade chronic inflammatory pathology, where visceral and epicardial adipose tissue generate high plasma levels of proinflammatory cytokines such as tumor necrosis factor-alpha (TNF-α) or C-reactive protein." (PMID 35887894, 2022). "Macrophages undergo significant changes during obesity; the overall number of macrophages increases due in large part to the recruitment of M1-polarized macrophages; in addition, they secrete cytokines, such as TNF-α, expressing a markedly pro-inflammatory phenotype." (PMID 36648872, 2022). "In obesity, DPP4 serum concentration was associated with increased macrophage infiltration of vWAT, high serum levels of leptin, and reduced adiponectin levels, as well as increased circulating levels of inflammatory cytokines, particularly IL-6, IL-12, and TNF-α." (PMID 36499312, 2022). "Tumor Necrosis Factor α (TNF) in particular may play a causal role in the development of anxiety-like behaviors, as blocking TNF signaling reduced the expression of anxiety-like behaviors induced by peripheral inflammation, chronic pain, obesity, or experimental autoimmune encephalomyelitis." (PMID 36104437, 2022). "Notably, adipokines may serve as a link between obesity and asthma, such as leptin, TNF-α, and IL-6." (PMID 36051916, 2022).
Obesity (continued). "Notably, Gram-positive beneficial microbes Bifidobacterium and Lactobacillus depleted in Ob/higher-Dep group are in line with their activity as they are reported to exhibit antidepressant and anti-obesity effects, and reduced levels of TNF-α in both clinical and animal studies." (PMID 35287577, 2022). "In addition, TNF-α and IL-6 mainly came from adipose tissue, which were significantly increased in adults with MetS as they were positively correlated with the degree of obesity." (PMID 35433780, 2022). "In this study, blood TNF-α and IL-6 levels increased, but it is highly possible that they were secreted from adipose tissue in addition to the damaged kidneys; thus, it is necessary to investigate the role of adipocytes both in inflammation as well as kidney damage during obesity and aging." (PMID 36289909, 2022). "Obesity paradox in surgical patients can be explained by various cytokines released by adipose tissue that may play key roles in protective effect against inflammation by regulating endovascular homeostasis and neutralizing tumor necrosis factor-α." (PMID 35802728, 2022). "Published literature shows that lotus leaf reduces the levels of inflammatory cytokines IL-1β, TNF-α, IFN-γ, and IL-6, increases the levels of anti-inflammatory cytokines IL-4 and IL-10, and inhibits inflammation caused by high-fat diets accompanied by obesity." (PMID 34992717, 2021). "The reduction of the secretion of IL-6 and TNF-α by V. opulus juice was observed in Saos-2 cells, therefore showing that the juice may be important not only for the metabolism of bone tissue but also may delay its demineralization resulting from obesity." (PMID 34279426, 2021). "Moreover, obesity refers to an excessive amount of adipose tissue, which is an important endocrine organ that secretes adipocytokines such as tumor necrosis factor-alpha (TNF-α), which can enhance insulin resistance and atherosclerosis in diabetic patients." (PMID 34443619, 2021). "This may be at least one molecular mechanism involved in the reduced B cell function in individuals with obesity, as it induces the secretion of pro-inflammatory cytokines (IL-6/TNF-α) in human peripheral blood B cells through activation of JAK2/STAT3 and p38MAPK/ERK1/2 signaling pathways." (PMID 33760825, 2021). "Thus, TNFα, IL-6, and CRP are well known markers of obesity-associated inflammation and disease." (PMID 33986456, 2021). "The current study could be extended by including the measurement of obesity-related plasma and tissue biomarkers such as adiponectin and C-reactive protein, inflammatory mediators such as TNF and functional changes in the colon such as short-chain fatty acid production." (PMID 34064139, 2021). "Interestingly, previous evidence has suggested that tumor necrosis factor (TNF), receptor-associated factor 6 (TRAF6), and enhancer of the zeste homolog 2 (EZH2) are key players in the upregulation of miR-429-3p in HFD-induced obesity." (PMID 34681631, 2021). "In obese exercised mice, expression of TNFα was significantly reduced as compared with both obese (P < 0.0001) and control mice (P < 0.05) (for positive and negative controls), suggesting that exercise has substantial beneficial effects alleviating inflammation in obesity." (PMID 33687595, 2021). "In addition, our results suggest that plasma adiponectin levels may play a more important role than TNFα in influencing plasma SHBG levels in our prepubertal population with obesity." (PMID 33689083, 2021). "In addition, obesity–related hypertension as well as various obesity-related hormones, such as leptin, adiponectin and tumor necrosis factor α could also be common links between obesity, cardiac remodeling and increased risk of AF." (PMID 34922449, 2021).